MDM2 (MDM2 proto-oncogene)
Diseases named in the same sentence as MDM2 in open-access papers (continued):
Sharing a sentence is not in itself a finding about the gene and the disease.
tumor (continued). "In addition, Manfredi showed that loss of Mdm2 enhanced tumour formation, which may result from a weak cell cycle arrest signal." (PMID 29337287, 2018). "However, MDM2 expression was significantly associated with tumor size (P = 0.028)." (PMID 24236052, 2013). "Finally, an important issue raised by the identification of MDM4 and MDM2 variants is the need to develop accurate detection systems able to distinguish the fl-MDM molecules from their variants in the tumor samples both at the levels of mRNA as well as of protein." (PMID 19721810, 2009). "Pancancer TCGA database analysis revealed MDM2 upregulation in the majority of tumor types compared with their corresponding normal tissues." (PMID 41510173, 2026). "We next analyzed associations between Livin and MDM2 and clinicopathological features (MPG score, Ki-67, age, lymph node status, tumor–node–metastasis (TNM) stage, ER, PR, and HER2) in pre- and post-NAC samples." (PMID 41551910, 2026). "These pathway-level changes were accompanied by reduced expression of transcripts frequently associated with tumor-promoting programs, such as SERPINA1, MDM2, PDGFA, TGFBR1/2, and SPINK1." (PMID 41596590, 2026). "Reported biomarkers exhibiting comparable dysregulation in both tumor and peritumor tissues include MDM2, E2F2, CDKN2A/p16, ETS-1, MGMT, and multiple microRNAs (e.g., miR-21, miR-96-5p, miR-145-5p)." (PMID 41683639, 2026). "Our experiments further demonstrated that the splicing regulation of exon 3 in MDM2 is a widely occurring splicing regulatory mechanism that promotes tumor cell proliferation and inhibits apoptosis in PitNETs." (PMID 41510173, 2026).
tumor (continued). "Among them, seven cancer genes (ERBB2, ERBB3, PPARG, MYC, CCND1, CCNE1, MDM2) were detected to be amplified in both ctDNA and tumor tissues, indicating the reliability of ctDNA in reflecting the genomic features of tumors." (PMID 40191434, 2025). "In colon carcinoma models, treatment with HDM201, another MDM2 inhibitor, increased T-cell-mediated tumor cell killing in vivo." (PMID 41299419, 2025). "The tumor exhibited 15% PD-L1 expression and strong MDM2 positivity, with an MDM2 copy number gain (CNG) of 9.15." (PMID 41246336, 2025). "Tumor-growth inhibition by the MDM2-siRNA complex was evaluated in peritoneal dissemination model mice." (PMID 41009451, 2025). "MDM2 also modulates the immune response within the tumor microenvironment, impacting T cell function, cytokine signaling, and antigen presentation." (PMID 41170373, 2025). "These experiments validated the potential use of the VH-HT3 intrabody as a therapeutic strategy for tumor suppression and provided a rationale for developing an MDM2 inhibitor." (PMID 40508092, 2025). "Among these regulators, the Mouse Double Minute 2 homolog (MDM2) oncogene exerts a crucial role in regulating both tumor metabolism and cellular survival mechanisms." (PMID 40046748, 2025). "There is a strong correlation between the MDM2 overexpression and increased VEGF-A levels in clinical cancer patient samples, implying a role for MDM2 in tumor angiogenesis." (PMID 39960347, 2025). "The therapeutic response to MDM2 inhibition is strongly influenced by the tumor microenvironment, encompassing immune regulation, metabolic adaptation, and stromal-immune crosstalk." (PMID 41170373, 2025). "Nutlin-2 and Nutlin-3a, which are structurally similar, both display significant anti-tumor activity, with Nutlin-3a being the most widely used Mdm2 inhibitor in research." (PMID 40427535, 2025). "Out of this patient cohort, 35 MDM2-amplified tumor samples were randomly chosen to further analyze the proteome." (PMID 41299419, 2025). "A case report involving a 59-year-old female with cardiac intimal sarcoma and multiple skeletal muscle metastases identified MDM2 oncogene amplification, suggesting its potential involvement in tumor development and metastasis." (PMID 41262307, 2025). "Pioneering studies developed PROTACs like MD-222 and MD-224, which recruit cereblon E3 ligase to facilitate MDM2 degradation, significantly enhancing anti-tumor activity compared to conventional inhibitors." (PMID 41170373, 2025). "Although clinical trials have shown that Mdm2 inhibitors possess anti-tumor activity and an acceptable safety profile, they come with limitations, including drug resistance and dose-limiting toxicities." (PMID 40277907, 2025).
tumor (continued). "Tumor-growth inhibition of the MDM2-siRNA complex was determined in the peritoneal dissemination model mice." (PMID 41009451, 2025). "To date, 72 MDM2 and 8 MDM4 mRNA splice variants have been identified; some of these are highly expressed in cancers and associated with tumor growth in vivo." (PMID 39960347, 2025). "MDM2 increases the tumor-promoting ERα levels while decreasing those of ERβ, a recently identified tumor suppressor that can decrease BC cell migration potential by upregulating adhesion protein expression." (PMID 40308267, 2025). "hMOF can directly interact with MDM2 and promote the accumulation of MDM2 by inhibiting its ubiquitination degradation, thereby inducing cisplatin resistance in tumor cells." (PMID 40164592, 2025). "We also determined the biological functions of MDM2 in CRC using the same CRC tumor tissue microarrays and confirmed the MDM2 expression in clinical samples via IHC staining (Cohort 2: n = 30)." (PMID 40611205, 2025).
tumor (continued). "This significant reduction in MDM2 is consistent with the observed inhibition of tumor growth and highlights the importance of MDM2 downregulation in the anticancer activity of MA242." (PMID 40046748, 2025). "Molecular insights into the tumor’s amplification of MDM2 and CDK4 suggest potential therapeutic targets for novel treatments such as CDK4/6 inhibitors and MDM2 inhibitors, which are currently under investigation." (PMID 40165894, 2025). "MDM2-FISH is recommended for high-risk cases, such as large or recurrent tumours in deep locations or older patients." (PMID 40564858, 2025). "These intrabodies bound to the MDM2 RING finger domain, specifically downregulating MDM2 activity and suppressing tumor proliferation via MDM2." (PMID 40508092, 2025). "There is an association between MDM2 expression in prostate cancer and the expression of MMP family proteins, especially MMP9, which promotes tumor cell migration by balancing pro-angiogenic mechanisms." (PMID 39759114, 2025). "One region stands out distinctly: a focal amplification on 12q centred on MDM2, showing markedly higher total and major copy number in NSD-Loss compared to NSD-Gain and SD tumours." (PMID 41509216, 2025). "We observed that the MDM2 methylation was associated with gender (p = 0.021), AFP (p = 0.011), number of tumors (p = 0.002), tumor size (p = 0.001), vascular invasion (p = 0.040) and TNM stage (p = 0.037)." (PMID 40432974, 2025). "As an oncogene/oncoprotein, mdm2 can initiate carcinogenesis and potentially drives uncontrolled tumor growth." (PMID 40452017, 2025). "MDM2 is a 56 kDa protein originally identified as a product of the mdm-2 gene, which is amplified in certain mouse tumor cell lines." (PMID 41226293, 2025).
tumor (continued). "Such molecules only target classical proteins such as VHL and MDM2,173 which means that there are still limitations in tumor treatment." (PMID 39759114, 2025). "Cellular (side) effects of an mdm2 targeting on immune-checkpoint expression is potentially relevant as they have the capacity to curb or even to block an endogenous immunological tumor defense." (PMID 40452017, 2025). "Immunohistochemical analysis suggested MDM2, CDK4, and P16 positivity in tumor cells, with MDM2 amplification confirmed in the mucinous area." (PMID 40826716, 2025). "Because MDM2 facilitatesTP53 degradation, upregulation of MDM2 lowersTP53 activity and tumor suppression." (PMID 40191734, 2025). "At present, a number of anti-tumor drugs targeting MDM2 have been developed, including APG-115, KRT-232, and ALRN-6924." (PMID 40335909, 2025). "The interaction of MDM2 with the tumor suppressor and E3 family member, von Hippel-Lindau, is notable in this context." (PMID 39960347, 2025). "In this study, we found that the MDM2-siRNA complex had a suppressive effect on MDM2-mRNA and tumor growth of peritoneal dissemination." (PMID 41009451, 2025). "MDM2 expression was localized in perivascular tumor regions, consistent with E3 ubiquitin ligase activity." (PMID 40926903, 2025).